H19 (H19 imprinted maternally expressed transcript)
Diseases named in the same sentence as H19 in open-access papers (continued):
Sharing a sentence is not in itself a finding about the gene and the disease.
glioma (continued). "MicroRNA-675, encoded in the first exon of H19, regulates cell proliferation and migration through CDK6, a pivotal regulator in cell cycle, in glioma and predicting a poor prognosis of glioma patients." (PMID 27063004, 2016). "On the other hand, several studies reported that H19 expression was positively correlated with glioma grading and that its expression is critical in tumor progression as well as invasion." (PMID 26230711, 2015). "The maternally expressed gene 3 (MEG3) lncRNA has also been correlated with gliomas, but in contrast to H19, the MEG3 levels are markedly decreased in gliomas, while its overexpression inhibits cell proliferation and promotes apoptosis in vitro." (PMID 25654223, 2015). "By analyzing gene expression data, H19 increased levels of expression were found in high grade glioma." (PMID 26448935, 2015). "Consistent findings are also seen in the context of GSCs, as H19 is one of the most highly upregulated lncRNAs in GSCs as compared to its differentiated counterparts of glioma cells." (PMID 26230711, 2015). "Having demonstrated the relationship between lncRNA H19 and miR-675 by our present data, the importance of miR-675 in lncRNA H19-mediated cell invasion is still unclear in glioma cells." (PMID 24466011, 2014). "In vitro experiment showed that deprivation of H19 expression remarkably reduced miR-675 expression in glioma cells." (PMID 24466011, 2014). "Such correlation is in agreement with the findings from the present study showing that H19 is the precursor of miR-675 in glioma." (PMID 24466011, 2014). "The effects of H19 RNA on the invasiveness and migration of glioma cells were checked by Transwell and wound healing assays." (PMID 24466011, 2014). "In the present study, we firstly showed the role of the H19/miR-675/CDH13 pathway in glioma development." (PMID 24466011, 2014). "In the current study, we explored the clinical feature, biological function and potential mechanism of lncRNA H19 in glioma." (PMID 24466011, 2014). "As a positive control for the in vivo binding of CTCF, we performed a ChIP assay in U87MG glioma cells using primers from the Imprinting Control Region of the human Igf2/H19 imprinted locus, which is known to have several CTCF binding sites." (PMID 21663659, 2011). "In addition, by performing K-M curve analysis, the expression of H19, HOTAIR, miR-148a-3p, miR-222-3p, MBP and HMGA2 had a significant association with glioma patients’ survival." (PMID 40351420, 2025). "However, the expression of the lincRNAs XIST, MALAT1 and H19, which are m6 A-modified transcripts, increased in glioma stem cells." (PMID 40382536, 2025). "This suggests that H19 could serve as a potential biomarker for the diagnosis and treatment for glioma diagnosis and treatment." (PMID 40004468, 2025). "Accumulating evidence has shown that H19 could regulate the development of glioma by activating the Wnt/β-catenin signaling pathway." (PMID 38355574, 2024). "Additionally, lncRNA H19 can also act as a ceRNA through the miR-138/HIF-1α axis to promote glioma angiogenesis." (PMID 38967893, 2024). "Alternatively, H19 could drive cell growth in glioma cells by sequestering miR-200a, which negatively regulates CDK6 expression." (PMID 37744274, 2023). "Therefore, more work is warranted to further characterize H19 in glioma and how it blunts let-7-mediated proliferative suppression." (PMID 37370851, 2023). "Existing research evidence has indicated that the lncRNA H19 may serve as a ceRNA to modulate miRNAs expression to regulate skin wound healing and glioma." (PMID 36787444, 2023). "Notably, H19, MALAT1, PVT1, and SBF2-AS1 have been associated with temozolomide resistance in glioma patients." (PMID 36819921, 2023). "We found that several lncRNAs, namely, AL606760.2, H19, MALAT1, PVT1 and SBF2-AS1 may function as glioma risk factors, whereas AC068643.1, AC079228.1, DGCR5, FAM13A-AS1, HAR1A and WDFY3-AS2 may have protective effects." (PMID 36819921, 2023).
glioma (continued). "In human glioma cells, the level of H19 increases, while the level of miR-152 decreases." (PMID 35345660, 2022). "Additionally, H19 active beta-catenin signaling, which in turn enhances expression c-Myc and Survivin protecting glioma cells from programmed cell death." (PMID 35955440, 2022). "H19/miR-675 signaling plays a critical role in glioma progression." (PMID 36246634, 2022). "In summary, these results suggested that H19 was up-regulated in glioma tissues and cells." (PMID 34796112, 2021). "Few studies have explored whether H19 is involved in the regulation of radioresistance in glioma cells." (PMID 34159190, 2021). "The up-regulation of lncRNA H19 in glioma cells, suggested it could function as one of the ceRNAs for miR-138, and thus promote angiogenesis, invasion, migration, and proliferation by increasing HIF-1α expression." (PMID 34646821, 2021). "In addition, both flow cytometry and 5-ethynyl-2′-deoxyuridine (EdU) assay suggested that H19 was involved in the cell cycle arrest, apoptosis, and DNA synthesis to modulate the radiation response of glioma cells and influenced their radioresistance." (PMID 34159190, 2021). "In consistence with these findings, our data revealed that H19 could enhance the aggressiveness of glioma cells by inhibiting the expression of miR-200a." (PMID 34796112, 2021). "Expression level of H19 is highly correlated with drug resistance in glioma cells." (PMID 34081618, 2021). "H19 has recently been found to be an independent posterior factor for low-grade gliomas." (PMID 34199840, 2021). "Besides, it has been reported that the H19 expression in glioma tissues is higher than that in para-carcinoma tissues and associated with poor prognosis of glioma patients." (PMID 34159190, 2021). "The expression level of H19 was positively correlated with glioma malignancy, and H19 could affect the immune infiltration level of glioma through changes in copy number." (PMID 34692695, 2021). "Circulatory biomarker: While circulatory H19 levels were a reliable prognostic indicator, to the best of our knowledge, their diagnostic value has not been investigated in glioma." (PMID 34322395, 2021). "H19 has a potential reference value for glioma remission and immunotherapy." (PMID 34899682, 2021). "In summary, our findings suggested that the expression of H19 was elevated in glioma, which could promote the growth, invasion and migration of tumor cells via H19/miR-200a/CDK6/ZEB1 axis." (PMID 34796112, 2021). "In addition, H19 acts as a miRNA precursor gene to promote glioma growth, which induces the production of miRNA-675 that further modulates expression of cancer-associated calmodulin 13 (CDH13)." (PMID 34081618, 2021). "LncRNA H19, which mediates the effect of curcumin in treating glioma accompanied by miR-675 and VDR, could act as a novel diagnostic biomarker." (PMID 34178684, 2021). "H19 has also been found to regulate glioma progression through miRNA-mRNA network." (PMID 34421359, 2021). "The evidence from the EdU incorporation assay supported that H19 could modulated the radiosensitivity of glioma cells, because repression of H19 could inhibit DNA replication activity after irradiation." (PMID 34159190, 2021). "Notably, treatment of gliomas with the drug Temozolomide showed survival of fewer glioma cells and analysis showed low expression levels of H19." (PMID 34081618, 2021). "Meanwhile, H19 rs2839698 was reported not to be associated with oral cancer, lung cancer, cervical cancer, glioma, and neuroblastoma." (PMID 33800276, 2021). "Additionally, knocking-down H19 suppressed the growth, migration, invasion, and cell cycle progression of glioma cells and increased apoptosis by attenuating Wnt/β-catenin signaling." (PMID 34421359, 2021). "H19 silencing by suppressing EMT via the Wnt/β-catenin pathway could reduce the resistance of human glioma cells to TMZ." (PMID 34178658, 2021).
glioma (continued). "Therefore, the upregulation of H19 postirradiation is of great importance for radiation response in glioma cells." (PMID 34159190, 2021). "Furthermore, qRT-PCR was performed to examine H19 expression in glioma cell lines (U87-MG and U251) compared to normal human astrocyte (NHAs)." (PMID 34796112, 2021). "Knockdown of H19 could induce the biological behavior changes of glioma cells by up-regulating miR-200a and down-regulating CDK6/ZEB1." (PMID 34796112, 2021). "The oncogenic role of H19 has been described in several malignancies, including adult gliomas." (PMID 34502082, 2021). "Together, these data demonstrated that H19 was an oncogene in glioma that could be a therapeutic target." (PMID 34421359, 2021). "Therefore, we investigated the effects and mechanism of action of lncRNA H19 on the homeostasis of glioma cells." (PMID 34796112, 2021). "Knockdown of H19 inhibited glioma metastasis in vivo and in vitro." (PMID 34322395, 2021). "Thus, the data demonstrated that the augment of H19 caused by radiation participated in the radiosensitivity regulation of glioma cells and downregulation of H19 increased the radiosensitivity of glioma cells." (PMID 34159190, 2021). "H19 expression was higher in glioma tissues and cell lines with a poor prognosis." (PMID 34977037, 2021). "Determining treatment response: TMZ-resistant glioma cell lines had higher H19 expression." (PMID 34322395, 2021). "This study articulated the upregulation mechanism of H19 in glioma cells exposed to X-rays and indicated that H19 might exert an influence on radiosensitivity of glioma cells through apoptosis, cell cycle arrest, and DNA synthesis." (PMID 34159190, 2021). "Therefore, we explored the relationship between lncRNA AC064875.1, AC131097.4, FLG-AS1, H19 and low-grade glioma and genomic instability using the CGGA mRNA-seq-693 dataset." (PMID 34081618, 2021). "To confirm that H19 plays a key role in the radiosensitivity of glioma, we further examined the H19 background level in T98G, U87, and U251 cells using real-time PCR and compared the radioresistance of these cell lines through performing a colony formation assay." (PMID 34159190, 2021). "In addition, Kaplan–Meier analysis of the Chinese Glioma Genome Atlas (CGGA) databases indicated a significant relationship between H19 overexpression and primary or recurrent glioma patients' survival rates." (PMID 34159190, 2021). "Recently, there are several studies on the expression and functions of H19 in glioma." (PMID 34796112, 2021). "Many glioma-related studies assumed that H19-derived miR-675 participates in diverse cellular processes including cell invasion, proliferation, migration, cell cycle, hypoxia tumor microenvironment, and development of glioma." (PMID 34159190, 2021). "As a first attempt to investigate whether H19 has an impact on the radioresistance of glioma, we first searched for relevant clinical data to analyse their relationship." (PMID 34159190, 2021). "Thus, our data indicated that H19 plays a key role in regulating the radiosensitivity of glioma cells." (PMID 34159190, 2021). "Another report showed that increased H19 expressed stimulated the tumorigenicity of glioma cells." (PMID 34421359, 2021). "Similarly, another study showed that H19 attenuated TMZ-resistance in glioma cells by inhibiting EMT via suppressing the Wnt/β-catenin pathway." (PMID 34421359, 2021). "In conclusion, the present study verified that radiation-induced CREB1 directly activated H19 transcription and upregulated H19 participated in radioresistance regulation of glioma cells via several cellular process, including apoptosis and G2/M phase arrest and DNA synthesis." (PMID 34159190, 2021). "They reported that H19, mediated by miR-675, promoted cell proliferation in glioma." (PMID 34421359, 2021). "In summary, our data revealed that knockdown of H19 may suppress the development of glioma in vivo by up-regulating miR-200a and down-regulating CDK6/ZEB1." (PMID 34796112, 2021).
glioma (continued). "H19 indeed acts as an enhancer of tumorigenesis and development in glioma." (PMID 34159190, 2021). "H19 also functions as ceRNA to regulate epithelial-to-mesenchymal transition by sponging miR-130a-3p, a critical biological process, which leads to polarization, migration, adhesion, and invasion in glioma cells." (PMID 32283739, 2020). "Interestingly, the expression level of H19 in serum-free cultured glioma cells was higher than that in serum cultured ones." (PMID 32081833, 2020). "As reported in related literature, H19 has a high expression in glioma tissues." (PMID 32081833, 2020). "In cell cultures, H19 promotes glioma-cell growth, invasion and proliferation, and angiogenesis." (PMID 32650527, 2020). "LncRNA H19 was up-regulated in glioma cells and predicted poor survival rates." (PMID 33298070, 2020). "Studies show that many lncNRAs had important effects on the immune microenvironment of gliomas, for example, lncRNA H19 could affect the level of immune infiltration of gliomas, as a result of affecting the prognosis of patients." (PMID 33330055, 2020). "The result is consistent with the finding in the previous study, revealing that H19 might act as a crucial regulatory role in glioma progression." (PMID 32081833, 2020). "Among them, there were five studies that met the screening criteria, and comprehensive analysis of the five studies showed that Median Rank=261, P-value =2.13E-11, indicating that H19 was highly expressed in glioma tissues and was mainly concentrated in GBM (P <0.01)." (PMID 32081833, 2020). "The result unearthed that H19 might sever as a possible molecular marker for predicting the degree of glioma malignancy." (PMID 32081833, 2020). "As an example, lncRNA H19 promoted the progression of glioma by targeting miR-140/Iaspp axis." (PMID 33298070, 2020). "Furthermore, it was found that the expression level of H19 in glioma tissues was clearly higher than that in the normal control group in each study (P <0.01)." (PMID 32081833, 2020). "Collectively, H19 may be involved in the occurrence and development of glioma, and has potential reference value for the relief and immunotherapy of glioma." (PMID 32081833, 2020). "Collectively, H19 has potential reference value for glioma remission and immunotherapy." (PMID 32081833, 2020). "H19-derived miR-675 might regulate glioma-cell proliferation and migration through cyclin dependent kinase 6 (CDK6) and Cadherin 13 (CDH13), and predict poor prognosis for patients with glioma." (PMID 32650527, 2020). "The lncRNA H19 promotes angiogenesis in glioma via the miR-138/HIF1α/VEGF axis." (PMID 33126510, 2020). "It was found that H19 could affect the immune infiltration level of glioma through copy number variations, thus affecting the prognosis of glioma patients." (PMID 32081833, 2020). "Additionally, studies demonstrated that H19 is overexpressed in glioblastoma and that this pattern promotes glioma cell invasion by activation of miR-675." (PMID 32283739, 2020). "Relevant reports exhibited that H19 promoted proliferation and invasion in human glioma cells." (PMID 32081833, 2020). "In another report from glioma cells, cell growth was arrested by H19 expression inhibition." (PMID 31404273, 2019). "Depletion of H19 inhibited glioma-provoked GEC proliferation, migration, and tube formation." (PMID 30116729, 2018). "Knockdown of H19 suppressed glioma induced angiogenesis by inhibiting miR-29a, which may modulate the onset of glioma by regulating biological behaviors of glioma vascular ECs." (PMID 29867565, 2018). "The H19-miR-675-HIF-1α loop network may provide a novel strategy for the hypoxia response in glioma." (PMID 28187439, 2017). "Additionally, H19 is overexpressed in temozolomide-resistant glioma cell lines and tumours, with knockdown of H19 increasing sensitivity in glioma cell lines." (PMID 28430163, 2017).
glioma (continued). "Studies have also demonstrated that H19 could potentially serve as an oncogenic lncRNA in different types of cancers, including gliomas." (PMID 28293170, 2017). "In addition, the expression profiles analysis in recurrent gliomas compared with primary gliomas identified abundant differentially expressed lncRNAs, such as H19, CRNDE, and HOTAIRM1." (PMID 28293170, 2017). "Indeed, knockdown of H19 inhibits glioma and induces endothelial cell proliferation, migration and tube formation by decreasing expression of miR-29a." (PMID 28187439, 2017). "The role of H19 in glioma has also recently been highlighted." (PMID 28187439, 2017). "We have shown that H19 is highly expressed in high grade gliomas." (PMID 26623562, 2016). "This difference could be due to different lncRNA molecular mechanisms: 1) H19 contains a microRNA (miR-675) in the first exon, which is responsible for its oncogenic activity by regulating the target genes of miR-675 in glioma and prostate cancer." (PMID 26989025, 2016). "In a larger study, it was found that H19/miR-675 expression correlates with glioma grade." (PMID 26623562, 2016). "H19/miR675 expression was significant higher in high grade glioma tissues than in low grade ones." (PMID 26623562, 2016). "Collectively, these data suggest that H19 regulates glioma development by deriving miR-675." (PMID 26448935, 2015). "SiRNA-induced H19 depletion inhibited invasion in glioma cells." (PMID 26448935, 2015). "H19/miR-675 signaling was recently identified as a critical pathway in glioma progression." (PMID 26448935, 2015). "By analyzing glioma gene expression data sets, we found increased H19 in high grade gliomas." (PMID 24466011, 2014). "In summary, H19 and its derivate miR-675 were positively correlated with glioma grade." (PMID 24466011, 2014). "We found that H19 was closely correlated with tumor grade in 3 different glioma data sets." (PMID 24466011, 2014). "Moreover, further study implies miR-675 largely abrogated the effect of si-H19 on elevating the invasion of glioma cells." (PMID 24466011, 2014). "H19 had been associated with glioblastoma and PVT1 had been associated with glioma." (PMID 24498199, 2014). "In this study, we identified that H19/miR-675 signaling was critical for glioma progression." (PMID 24466011, 2014). "The oncogenic function of H19/miR-675 signaling may serve as the potential target for glioma therapy." (PMID 24466011, 2014). "And H19 regulated glioma cell invasion by deriving miR-675 and inhibited CDH13." (PMID 24466011, 2014). "Finally, introduction of miR-675 abrogated H19 knockdown-induced cell invasion inhibition in glioma cells." (PMID 24466011, 2014). "Other studies on curcumin have shown that in glioma, breast, gastric, and hepatocellular cancers, this natural compound reduces the aggressiveness of cancer cells by inhibiting the expression of H19, an oncogenic lncRNA also involved in the cisplatin response from melanoma cells." (PMID 40282449, 2025). "Thus, H19 inhibits glioma cell apoptosis through the H19/miR-675/VDR feedback loop." (PMID 38355574, 2024). "Moreover, H19 knockdown suppresses glioma growth in a xenograft nude mouse model." (PMID 37190145, 2023). "Interestingly, one of the other shown lncRNA, H19 also seems to affect EMT in glioma cells." (PMID 35402278, 2022). "Analysis showed that lncRNA H19, AC091932.1, AC064875.1, AC010273.2, and AC131097.4 were negatively correlated with overall survival, indicating that they are risk factors for low-grade glioma, therefore, high expression levels of the lncRNAs are associated with poor prognosis." (PMID 34081618, 2021). "In this study, H19 could regulate the growth and metastasis of glioma by targeting miR-200a." (PMID 34796112, 2021). "Furthermore, H19 expression is closely related with glioma grade." (PMID 33980320, 2021). "Knockdown of H19 could enhance the sensitivity of human glioma cells to TMZ." (PMID 34178658, 2021).